IGLV3-21 (immunoglobulin lambda variable 3-21)
Description:
V region of the variable domain of immunoglobulin light chains that participates in the antigen recognition. Immunoglobulins, also known as antibodies, are membrane-bound or secreted glycoproteins produced by B lymphocytes. In the recognition phase of humoral immunity, the membrane-bound immunoglobulins serve as receptors which, upon binding of a specific antigen, trigger the clonal expansion and differentiation of B lymphocytes into immunoglobulins-secreting plasma cells. Secreted immunoglobulins mediate the effector phase of humoral immunity, which results in the elimination of bound antigens. The antigen binding site is formed by the variable domain of one heavy chain, together with that of its associated light chain. Thus, each immunoglobulin has two antigen binding sites with remarkable affinity for a particular antigen. The variable domains are assembled by a process called V-(D)-J rearrangement and can then be subjected to somatic hypermutations which, after exposure to antigen and selection, allow affinity maturation for a particular antigen.
Synonyms: IGLV321; V2-14
Tractability: Antibody: its Gene Ontology location is reachable by antibodies, with high confidence; UniProt places it where antibodies can reach, with medium confidence; UniProt predicts a signal peptide or a membrane-spanning region.
Gene: Immunoglobulin variable (V) gene on chromosome 22 (22,711,689 to 22,713,203, forward strand). Ensembl gene ENSG00000211662.
Subcellular location: Secreted; Cell membrane
Pathways (Reactome):
Immune System: Antigen activates B Cell Receptor (BCR) leading to generation of second messengers; CD22 mediated BCR regulation; Classical antibody-mediated complement activation; FCERI mediated Ca+2 mobilization; FCERI mediated MAPK activation; FCERI mediated NF-kB activation; FCGR activation; Fc epsilon receptor (FCERI) signaling; Immunoregulatory interactions between a Lymphoid and a non-Lymphoid cell; Initial triggering of complement; Regulation of Complement cascade; Regulation of actin dynamics for phagocytic cup formation; Role of LAT2/NTAL/LAB on calcium mobilization; Role of phospholipids in phagocytosis
Disease: FCGR3A-mediated IL10 synthesis; FCGR3A-mediated phagocytosis; Potential therapeutics for SARS
Hemostasis: Cell surface interactions at the vascular wall
Vesicle-mediated transport: Scavenging of heme from plasma
Gene Ontology:
Molecular function: antigen binding
Biological process: immune response
Cellular component: blood microparticle; extracellular exosome; extracellular region; immunoglobulin complex; plasma membrane
Homologues: Paralogues in human: IGLV3-12 (85% identical), IGLV3-9 (85% identical), IGLV3-1 (73% identical), IGLV3-25 (70% identical), IGLV3-10 (68% identical), IGLV3-16 (67% identical), IGLV3-22 (66% identical), IGLV3-27 (64% identical), IGLV3-19 (63% identical), IGLV3-32 (63% identical), IGLV1-40 (62% identical), IGLV1-51 (61% identical), and 81 more.
Diseases named in the same sentence as IGLV3-21 in open-access papers:
IGLV3-21 is named in the same sentence as 1 disease in open-access papers, as found by Europe PMC text mining. Sharing a sentence is not in itself a finding about the gene and the disease. The quoted sentences say what the papers report.
chronic lymphocytic leukemia (1 paper, 2021). "Likewise, IGLV3-21, an important paralog of IGLV3-22, was confirmed to be a risk factor for chronic lymphocytic leukemia." (PMID 34133324, 2021).